CCNA1 (cyclin A1)
Diseases named in the same sentence as CCNA1 in open-access papers (continued):
Sharing a sentence is not in itself a finding about the gene and the disease.
cancer (continued). "This study, for the first time, presents CCNA1 and TIMP3 hypermethylation as a helpful tool to identify HNSCC subjects at risk of developing second primary carcinomas." (PMID 24359512, 2013). "HPV-HNCs up-regulated, relative to HPV+ cancers, a small set of cell cycle-specific genes, including cyclin D1/D2 (CCND1 and CCND2; G1 associated) and cyclin A1 (CCNA1)." (PMID 21447181, 2011). "First, the expression of CCNA1 has been demonstrated to be downregulated in several cancers, such as nasopharyngeal carcinoma and head and neck squamous-cell cancer (HNSCC)." (PMID 16524460, 2006). "Notably, CCNA1 was significantly upregulated in PTC samples, supporting its role as a diagnostic marker and aligning with its established association with other cancers." (PMID 40722651, 2025). "Considering these discoveries, both KDM8 and CCNA1 are potential targets for cancer treatment." (PMID 37893043, 2023). "In addition, FcγRIIIa expression correlated with cyclin A1 in cancer tissues from the same patient cohorts (P = 0.001)." (PMID 34932854, 2022). "However, relevance for the tumor suppressor gene CCNA1 has been reported in other HPV induced cancer, e.g., cervical and HNSCC." (PMID 34944992, 2021). "Interestingly, among the possible methylation biomarker candidates in both HPV-associated cancers, CC and HNSCC, three genes were considered by different groups: CDH1, CCNA1, and RASSF1." (PMID 34835040, 2021). "Whereas 60% and 36.6% of the microinvasive cancers and high SILs, respectively, demonstrated CCNA1 methylation, none of the HPV-associated low SILs exhibited these epigenetic changes." (PMID 16524460, 2006). "Moreover, KDM8 has been revealed to positively regulate CCNA1 in cancer cell proliferation." (PMID 37893043, 2023). "CCNA1 might control the cell cycle, and contributes to cancer invasion and metastasis." (PMID 32532105, 2020). "Interestingly, cyclin A1 was shown to induce cell arrest and apoptosis in carcinoma cells." (PMID 28340577, 2017). "We found that FDI-6 and FOXM1 shRNA impaired Olaparib-induced expression of CDK1, CCNA1, CCNB1, and CDC25B to inhibit the mitosis of cancer cells." (PMID 34880209, 2021). "Considering CD1A is an immune regulatory gene and CCNA1 is involved in response pathways to HPV infection, it is plausible that these genes would play a larger role in more antigenic cancers with a viral etiology." (PMID 26518708, 2015). "We observed a statistically significant correlation between cyclin A1 and VEGF in cancer specimens from the two patient cohorts (In the 94-patient cohort: r2=0.362, p<0.01; and in the 48-patient cohort: r2=0.288, p<0.01)." (PMID 23991063, 2013). "There is a statistically significant correlation between cyclin A1 and VEGF expression in the cancer specimens from the two patient cohorts." (PMID 23991063, 2013). "The methylation frequency of each gene ranks with only a few other genes methylated at high frequency in CRC (Cyclin A1, CDX1, RAR-β, MYOD1, p15INK4b and COX-2) in a cancer-specific manner." (PMID 19662090, 2009). "However, in SCA patients, the effect of PBK, LCN2 and CCNA1 expression on cancer progression was not statistically significant (p > 0.05)." (PMID 32693821, 2020). "Whereas complete methylation could be observed in most cancer cells, partial and non-methylated CCNA1 was discovered in the adjacent epithelia." (PMID 16524460, 2006).
tumor (65 papers, 2006 to 2026). "In this study, the observed increased expression of the CCNA1 gene in the PTC group compared to other thyroid tissues supports its involvement in tumor progression and highlights its potential as a diagnostic marker for PTC." (PMID 40722651, 2025). "Critical genes within the Hallmark Apoptosis pathway, such as ERBB2 (HER2) and CCNA1 are crucial for regulating tumor aggressiveness and responsiveness to therapy." (PMID 39000413, 2024). "TIMP3 and CCNA1 hypermethylation was significantly associated with lower rates of second primary tumor-free survival (p = 0.007 and p = 0.001; log-rank test, respectively)." (PMID 24359512, 2013). "In particular, CCNA1 was significantly upregulated in one tumor and significantly downregulated in one other tumor tissue of the three tumors tested." (PMID 35681633, 2022). "A previous study reported that methylation of CCNA1, a tumor suppressor gene, can differentiate between low and high grade lesions." (PMID 32102526, 2020). "Previous studies have demonstrated that the activity of ERK was responsible for the aberrantly expression of cyclin A1 and p27 in human tumor cells." (PMID 33324557, 2020). "Cyclin A1 protein was homogeneously expressed in 43 of 62 grade 3 tumor samples and in 1 of 10 grade 2 specimens (p < 0.001)." (PMID 26499264, 2015). "We further observed that VEGFR1 expression was in general higher in both endothelial cells of blood vessels and tumor cells from tumors that overexpressed cyclin A1." (PMID 23991063, 2013). "At the end of experiments, tumors that overexpressed cyclin A1 were significantly larger, with a mean tumor volume of 119±28 mm3, compared with the tumors that expressed control vector, with a mean size 25.9±17 mm3 (p<0.01)." (PMID 23991063, 2013). "There was a higher proportion of ER-α positive tumor cells in xenograft tumors that overexpressed cyclin A1 compared with the tumors expressed control vector." (PMID 23991063, 2013). "We then established xenograft mice in which a larger number of tumor cells which constitutively overexpressed cyclin A1-pcDNA or control-pcDNA vectors were subcutaneously implanted into mice." (PMID 23991063, 2013). "In our collective, patients with Cyclin A1 promoter methylation in their corresponding tumor samples tended to have improved progression-free and overall survival but without statistical significance (data not shown)." (PMID 22712549, 2012). "This would enable the virus to down regulate the tumor suppressive properties of Cyclin A1 on the one hand and to have nevertheless the possibility of promoting cell cycle progression through Cyclin A1 on the other hand." (PMID 22712549, 2012). "MeDIP-qPCR and qPCR were performed to measure demethylation status and mRNA re-expression level of 7 tumor-suppressor genes (CCNA1, CHFR, FHIT, PAX1, PTEN, SFRP4, TSLC1) in Hela and Siha cells after silencing DNMT1." (PMID 21999220, 2011). "Additionally, the increased p-ERK1/2, cyclin A1 and decreased p27 protein levels were observed in xenografted tumor tissues that derived from SiHa-HK2 and HeLa-HK2 cells." (PMID 33324557, 2020). "Here, we test the hypothesis that specific candidate gene methylation markers (CCNA1, NDN, CD1A, DCC, p16, GADD45A) are associated with tumor recurrence and survival, in a well-characterized, prospective, cohort of 346 HNSCC patients." (PMID 26518708, 2015). "Cyclin A1 expression was analyzed immunohistochemically in tumor material from 72 patients primarily with advanced EOC who underwent cytoreductive surgery followed by platinum-based chemotherapy (carboplatinum/paclitaxel in 71 patients, cisplatinum/paclitaxel in one patient)." (PMID 26499264, 2015). "However, comparison of the tumor-adjacent gastric tissue between HP+ and HP- patients revealed 8 differentially methylated CpG sites located within 7 genes (CCNA1, CSPG2, DAB2IP, DIO3, FLT1, STAT5A and TWIST1)." (PMID 24674026, 2014).
tumor (continued). "As elevated level of VEGF signalling may enhance angiogenesis and promote tumor cell invasion, the altered VEGF expression in MCF-7 cells that overexpress cyclin A1 may contribute to tumor cell invasion." (PMID 23991063, 2013). "Significant tumour specific methylation of cyclin A1 promoter was also seen." (PMID 16449996, 2006). "The longer TTP in patients with higher Cyclin A1 levels might therefore reflect responsiveness to cytostatic treatment rather than an association between more aggressive tumor biology and later-stage disease at first diagnosis." (PMID 26499264, 2015). "According to human data derived from the TCGA and GTEx databases, decreased expressions of miR-4516 and increased expressions of Wnt 8B, DVL3, FOSL1, CCNA1, CCNB1, CDK1, and CDK2 in tumor tissue contributed to the progression of LUAD." (PMID 38930863, 2024). "The expressions of miR-4516 were lower, while the expressions of Wnt 8B, DVL3, FOSL1, CDK1, CDK2, CCNA1, and CCNB1 were enhanced in tumor tissue compared to normal lung tissue in the human samples." (PMID 38930863, 2024). "At the beginning, we used immunohistochemical stain analysis to determine the expression status of the KDM8 and CCNA1 protein in 27 OSCC samples TMA and 5 normal oral mucosa samples adjacent to the tumor." (PMID 37893043, 2023). "The expression levels of cyclin A1 and CDK2 in the tumor tissues of the models were detected with qRT-PCR." (PMID 34992655, 2021). "Among these, CCNA1 and STMN2, which we found to be upregulated in the non-tumor infected patient-derived organoids, were previously identified to be upregulated in HCC." (PMID 34328417, 2021). "The present study demonstrates that MYC, CCNA1, and BIRC7 alterations are significantly enriched in depressed neoplasms." (PMID 32532105, 2020). "The sensitivity, specificity, and accuracy of the D-marker panel for discriminating the depressed from the polypoid neoplasms and the arm-level changes in MYC, CCNA1, and BIRC7 in each case in the discovery set were calculated." (PMID 32532105, 2020). "Depressed neoplasms seem to arise via a distinct molecular pathway, in which alterations in MYC, CCNA1, and BIRC7 play a significant role." (PMID 32532105, 2020). "We used MYC, CCNA1, and BIRC7 in combination as a D-marker panel for identifying depressed neoplasms, and tested the panel in the discovery set." (PMID 32532105, 2020). "CNAs in MYC, CCNA1, and BIRC7 were significantly enriched in depressed neoplasms and designated as the D-marker panel." (PMID 32532105, 2020). "Notable interactions between CCNA1 and CDK1 and CCNA1 and CDK2 demonstrate the contribution of CCNA1 in the progression of cell proliferation and tumor growth, but only when involved with the kinases." (PMID 33182737, 2020). "Genes favoring tumor growth and cell proliferation, CD40 and CCNA1 were significantly downregulated in treated cells (p < 0.05)." (PMID 31349612, 2019). "With provided TF-TG correlation coefficient, users get TF list targeting CCNA1, CCNA2 and see that the correlation coefficients are different between normal samples and selected tumor samples." (PMID 29504910, 2018). "With ‘TF regulation’ checked, TF-TG correlation coefficients are provided and then user can get the TFs targeting CCNA1, CCNA2 and see that the correlation coefficient between FOXP3 and CCNA2 is much different in normal samples (0.58) and tumor samples (0.16)." (PMID 29504910, 2018). "Western blot analysis also demonstrated the same trend, with the expression of Cyclin A1 and CDK2 being downregulated in the tumor tissues of the HSA-372 group of nude mice." (PMID 26673619, 2016).
tumor (continued). "All of these genes are known to be involved in different aspects of breast carcinogenesis, which includes tumor suppression, HIC1, CDH1, CDH13, CDKN2, DNA repair, MGMT, apoptosis, PYCARD, TNFRSF10C, and cell cycle regulation, CCNA1." (PMID 25403427, 2014). "A total of 219 CpG sites (185 hypermethylated and 34 hypomethylated) in 147 unique genes were significantly differentially methylated between tumor and tumor-adjacent gastric tissue (FDR = 0.001), with the top three CpG sites located in HOXA5, SFRP1 and CCNA1." (PMID 24674026, 2014). "After adjusting for age, sex, tumor site, and tumor stage, HPV(+) tumors were found to be, on average, 9.6% more methylated at the CCNA1 promoter compared to HPV(−) tumors (p = 0.029)." (PMID 23358896, 2013). "To further validate the role of cyclin A1 and its functional link with VEGF and ER-α in tumor growth and angiogenesis, we generated MCF-7 cells that were stably transfected with cyclin A1-pcDNA or control-pcDNA vector." (PMID 23991063, 2013). "We show that xenograft tumors that overexpress cyclin A1 display increased expression of VEGF and VEGFR1 in the tumor cells and in endothelial cells of blood vessels." (PMID 23991063, 2013). "Using xenograft mouse models in which mice were implanted with MCF-7 xenograft tumor cells, we showed that MCF-7 xenograft tumors that overexpressed cyclin A1 grow into larger size than the tumors expressed control vectors." (PMID 23991063, 2013). "A total of 15 genes (AIM1, ARF, CCNA1, MGMT, hMLH1, PGP9.5, S100A2, APC, RAR-β2, ER-α, ER-β, MCAM, VGF, FKBP4 and SSBP2) were analysed for promoter methylation using QMSP in 57 tumour samples, comprising 43 SEs and 14 NSEs, and 23 NT samples." (PMID 22068818, 2012). "Performing QMSP with a panel of three genes (CDKN2A, CCNA1 and DCC), we found 64% of HNSCC tumours were hypermethylation informative." (PMID 18594522, 2008). "Moreover, elevated CCNA1 and CCNA2 expression levels activates the PI3K/AKT pathway, promoting tumor growth and cell survival." (PMID 38384287, 2024). "This study compared the expression levels of miR-4516, Wnt 8B, FZD2, DVL3, FOSL1, CDK1, CDK2, CCNA1, and CCNB1 in primary LUAD tumor tissue with those in normal lung tissue using data from The Cancer Genome Atlas (TCGA) database to assess the consistency of our findings with the human sample." (PMID 38930863, 2024). "The expression of CCND1 and CCNA1 was even more prominently elevated in the tumor region than in the non-tumor tissues in Atg7ΔHep mice." (PMID 32382012, 2020). "Although we could not identify the responsible genes that promoted transcription of CCNA1 and CCNA2, we found that positive correlation between FOXP3 as TF and CCNA2 as TG is disrupted in tumor samples." (PMID 29504910, 2018). "Besides, different from CCNB1, CCNA1 functions in S and G2/M phases, which is due to its two different phosphorylated substrates, CDK1 and CDK2, subsequently conducing tumor cells proliferation." (PMID 26999101, 2016). "Other criteria, which are not specific to the targeted tumor entity and apply to Cyclin A1, are an intracellular location and a high number of available epitopes." (PMID 26499264, 2015). "We pursued a reverse strategy by first selecting the testis-selective antigen Cyclin A1 and then screening its expression in a multitude of different non-hematological tumor entities." (PMID 26499264, 2015). "To elucidate the biologic relationship of CCNA1 silencing in the context of UCC, we performed different in vitro assays and our data is consistent with our findings in human primary LGPUCC that CCNA1 is a potential tumor suppressor gene." (PMID 24980822, 2014). "Our findings suggest that cyclin A1 may promote invasive tumor phenotypes by recruiting VEGF and VEGFR1 in tumor cells." (PMID 23991063, 2013).
tumor (continued). "By Spearman correlation test, eight genes (AIM1, CCNA1, MCAM, PGP9.5, hMLH1, ARF, VGF and APC) showed to be independent of each other and were selected to be included in a logistic regression model, which predict the probability of tumour." (PMID 22068818, 2012). "Promoter methylation was significantly elevated in tumours compared to normal tissue for p16 (P=0.048), cytoglobin (P=0.002) and cyclin A1 (P=0.001) but not in RARβ (P=0.088) or E-cadherin (P=0.347)." (PMID 16449996, 2006). "These genes, including ERBB2, CCNA1, FOXC2, LEFTY2, VTN, ACKR3, and PTGS2, are involved in key processes like apoptosis, epithelial–mesenchymal transition, angiogenesis, response to hypoxia, and KRAS signaling pathways, which are crucial for tumor virulence and the spread of metastases." (PMID 39000413, 2024). "Among these genes are ERBB2, CCNA1, FOXC2, LEFTY2, VTN, ACKR3, and PTGS2, which influence processes such as apoptosis, epithelial–mesenchymal transition, angiogenesis, hypoxia responses, and KRAS signaling pathways, all vital for tumor aggressiveness and metastatic spread." (PMID 39000413, 2024). "Although patients without neoplasia were selected, aberrant methylation of the CCNA1, DAPK, DCC and MGMT genes was present in the pretreatment oral rinse samples in all participants of both groups, an epigenetic event that is the target of action of valproic acid." (PMID 34385507, 2021). "Moreover, the increased protein levels of p-Raf-1, p-MEK1/2, p-ERK1/2, and cyclin A1 and the decreased protein level of p27 were also observed in six SiHa-HK2 or HeLa-HK2 cells derived xenografted tumor tissues, compared to their control groups (SiHa-GFP and HeLa-GFP, p<0.05)." (PMID 33324557, 2020). "The vast majority of genes were equally expressed in tumor and non-tumoral, control pituitary glands, including CCNL1, CCNE2, CCNB2, CCNA1, CDK18, CDK19 and CDK20." (PMID 35260162, 2022). "We tested the promoter methylation of CCND2, CCNA1 and CALCA in urine sediment DNA from primary UCC cases and subjects without any neoplastic disease (controls/normals)." (PMID 24980822, 2014). "Irrespective of the relationship with HPV16 shown herein, Cyclin A1 expression predicts recurrence rate in HNSCC and should therefore be considered as a possible tumor marker." (PMID 22712549, 2012). "RT-PCR analysis of the transcriptional expression of cell cycle genes showed a significantly increased expression of ccnA1, ccnB2, ccnD3, ccnE1, cdc25b, and E2F1 and a significantly decreased expression of ccnD2 in the Fhit-transfected versus non-transfected tumor cells." (PMID 32545680, 2020). "MGMT, VGF, CCNA1 and FKBP4 are interesting, as they could be specific for tumours as all of the normal samples showed no methylation, and in addition, hMLH1 that had only one positive in normal." (PMID 22068818, 2012).
head and neck tumor (2 papers, 2013). "To validate our findings of increased CCNA1 methylation HPV(+) tumors, we quantified methylation at 4 CpG sites in the promoter region of CCNA1 in an additional 128 pretreatment head and neck tumors." (PMID 23358896, 2013). "This analysis revealed that hypermethylation of CCNA1, DAPK, MGMT, SFRP1 and TIMP3 was frequent in head and neck tumor (40-70%)." (PMID 24359512, 2013).
infection (2 papers, 2020 to 2023). The state of being infected such as from the introduction of a foreign agent such as serum, vaccine, antigenic substance or organism. "Similarly, cyclin A1 (CCNA1) promoter hypermethylation, probably induced by the infection of HPV, is common in CC and the decreased gene expression is specific to the invasive phenotype, suggesting a potential role of CCNA1 for early diagnosis of invasive CC." (PMID 37368179, 2023).
muscular disorders (1 paper, 2013). "Importantly, cyclin A1 RNA levels of FSHD were not only higher compared to healthy controls but also to patients with the other muscular disorders: CAV3, DYSF, and FHL1." (PMID 24019929, 2013).
myopathies (1 paper, 2013). "In our microarray assays, CCNA1 expression was detectable at very low levels in healthy controls as well as in some other myopathies such as CAV3, DYSF and FHL1." (PMID 24019929, 2013).